VEGFA (vascular endothelial growth factor A)
Diseases named in the same sentence as VEGFA in open-access papers (continued):
Sharing a sentence is not in itself a finding about the gene and the disease.
Obesity (continued). "The activated VEGFA signaling and increased adipose vascularity provide cells which can differentiate into beige (anti-obesity) or white (pro-obesity), and RA is important in driving these cells to differentiate into beige adipocytes to prevent obesity." (PMID 29021914, 2017). "When VEGFA is overexpressed in adipose tissue, it results in increased blood vessel number and size, protection against high-fat diet–induced hypoxia and obesity, and improves whole-body insulin sensitivity and glucose tolerance." (PMID 29196658, 2017). "Obesity involves angiogenesis in which vascular endothelial growth factor-A (VEGF-A) plays a key role." (PMID 22206010, 2011). "Notably, adipose tissue-specific overexpression of VEGFA confers protection against diet-induced obesity and insulin resistance in murine models." (PMID 41010281, 2025). "Obesity also increased intestinal permeability, metabolic endotoxemia, cytokines, and VEGFA." (PMID 36406423, 2022). "Computational functional analysis performed with miRNAs that were altered in WD dams has suggested a relevant role of the miRNAs modulating the expression of genes involved in the VEGFA-VEGFR2 signaling pathway, which is associated with obesity-related metabolic diseases." (PMID 35740314, 2022). "Moreover, it has been described that VEGFA expression was not only affected by menopausal status and BMI, but among perimenopausal women with cardiometabolic diseases, combined with obesity, the polymorphic changes in the VEGFA influence its expression." (PMID 36230822, 2022). "Lower capillary density but unaltered VEGFA levels in the skeletal muscle of patients with obesity have been reported in a human clinical trial, suggesting the role of other signaling pathways in obesity-induced capillary rarefaction." (PMID 33327460, 2020). "This creates a challenge in determining if VEGFA is an optimal therapeutic target in obesity." (PMID 33327460, 2020). "Levels of VEGFA and CSF-1 measured in cerebrospinal fluid have been found to be positively associated with BMI43 and the VEGFA gene is found to be mediating the connection between obesity and breast cancer." (PMID 33082373, 2020). "The underlying protective mechanisms of VEGFA in an experimental model of steatosis induced by CDD were similar to those described in the genetic obesity model (data not shown)." (PMID 31254006, 2019). "Furthermore, our results also revealed several common upstream regulators associated with immune regulation and resistance to obesity (IL-4, IL-5, IL-33, CD15, HGF, ANGPT2, VEGFA, and neuropilin 1 [Nrp1]), supporting a critical role of intestinal homeostasis in systemic pathogenesis of obesity." (PMID 36880999, 2023). "In obesity, the TME causes NLRC4 inflammasome activation in TAMs, leading the production of the pro-inflammatory cytokine IL-1β, which then promotes the angiogenesis of trophoblast tumor cells through adipocyte-mediated vascular endothelial growth factor A (VEGFA) expression." (PMID 37497237, 2023). "Moreover, a number of candidate genes previously linked through GWAS to T2DM and obesity were found to be differentially expressed in the adipose tissue from discordant twins, including PPARG, GLIS family zinc finger 3 (GLIS3) (T2DM), vascular endothelial growth factor A (VEGFA), and IRS1 (obesity)." (PMID 32653024, 2020). "Obesity might aid the progression of cancer through the pathways linked with NLRC4 and VEGFA." (PMID 33167967, 2020). "Key genes within locus 6.52, including VEGFA, SRF, and GNMT, established a link between obesity and chronic ischemic heart disease." (PMID 40565603, 2025). "In this context, obesity and CC also increased the levels of relevant inflammation and ECM remodelling factors including IL-6, OPN, YKL-40 and VEGFA." (PMID 34445187, 2021).
Obesity (continued). "On the contrary, three genes involved in angiogenesis and one involved in energy homeostasis were up-regulated in thew SAT of individuals with normal weight compared to individuals with obesity; DLL4, PLIN2, VEGFA and PNPLA2." (PMID 33022994, 2020). "In contrast with the genetic deletion of Vegfa, both the constitutive overexpression and inducible overexpression of VEGFA resulted in increased vascular density in AT and protected the transgenic mice against HFD-induced obesity and insulin resistance." (PMID 33327460, 2020). "As in the genetic obesity model (Zucker rats), in CDD-SD rats, hepatic VEGFA protein levels were lower in the PH+I/R group than in the Sham group (Online Resource 3)." (PMID 31254006, 2019). "RT-qPCR results showed that, compared with the control group, mRNA expression levels of VEGFA, VEGFR-2, CD31, and SIRT1 were significantly decreased in the obesity group (P < 0.001), while the expression levels of GLUT1, HIF-1α, TNF-α, IL-6, HMGB1, and TLR4 were significantly upregulated (P < 0.01)." (PMID 41505418, 2026). "Thus, results suggest a low-grade inflammatory state in VEGFA, CSF-1 and CCL3 which is related to obesity and BMI." (PMID 33082373, 2020). "In contrast to AT, VEGFA levels do not seem to contribute to capillary rarefaction in some other tissues during the progression of obesity." (PMID 33327460, 2020). "Adipose tissue HIF1A activity is influenced by multiple signals, including adipogenesis, insulin, hypoxia, and obesity, but the induction of HIF1A by E2 can induce VEGFA and thereafter promote angiogenesis, a process that is required for adipocyte differentiation and adipose tissue growth." (PMID 29196658, 2017). "As opposed to its angiogenic isoforms, VEGFA also has inhibitory isoforms such as VEGFA165b, which are upregulated in obesity, counteracting the pro-angiogenic effects and promoting vascular rarefaction in the vWAT of patients with obesity." (PMID 33327460, 2020). "In the context of obesity, the tumor microenvironment induces an enhanced level of tumor-infiltrating myeloid cells with an activated NLRC4 inflammasome which further activates IL-1b, thus driving progression of disease through adipocyte-mediated VEGFA expression and angiogenesis." (PMID 33167967, 2020).
osteosarcoma (238 papers, 2006 to 2025). A usually aggressive malignant bone-forming mesenchymal neoplasm, predominantly affecting adolescents and young adults. "The results of the survival analysis revealed that VEGFA as a risk factor in osteosarcoma treatment." (PMID 38086608, 2024). "VEGFA is involved in angiogenesis, progression, and metastasis in various malignancies, including osteosarcoma, and has a strong association with a poor prognosis." (PMID 36618348, 2022). "The specific binding of LC09 ensured the delivery of CRISPR/Cas9 to lung metastasis and orthotopic osteosarcoma, thus causing efficient VEGFA genome editing in cancer cells and inhibiting both types of tumors." (PMID 32659966, 2020). "Loss of miR-497 induced drug resistance through targeting vascular endothelial growth factor A (VEGFA) in osteosarcoma." (PMID 28978183, 2017). "The authors used an osteosarcoma cell-specific aptamer LC09 to generate a LC09-functionalized PEG-PEI-Cholesterol (PPC) lipopolymer capable of capturing CRISPR/Cas9 plasmids that encoded for VEGFA gRNA and Cas9." (PMID 35164379, 2022). "Similarly, a genetic amplification of the VEGFA gene was detected in osteosarcoma and significantly associated with high microvessels density and low patient disease-free survival." (PMID 31370265, 2019). "In human tumors, the presence of elevated VEGF correlates with a worse overall survival and a potential for an increase in pulmonary metastasis, and approximately 20–25% of human osteosarcomas contain a VEGFA amplification." (PMID 40374715, 2025). "Additional predicted targets of miR-30a and miR-30e within this pathway include PIK3CA, mTOR, FOXO3, MMP13, SOX9, BCL2, VEGFA, and CCND1, all of which have been previously associated with osteosarcoma pathogenesis." (PMID 40862758, 2025). "S1P has been demonstrated to enhance VEGFa gene expression in ECs and osteosarcoma cells, and S1PR3 to promote bone matrix formation and mineralization in OBs,17 respectively." (PMID 38477738, 2024). "Another study showed that MicroRNA‐134 attenuated osteosarcoma angiogenesis and proliferation via inhibiting the VEGFA/VEGFR1 signaling pathway." (PMID 38086608, 2024). "lncRNA LINC01116 can target miR‐520a‐3p and VEGFA and arrest cell proliferation and preclude brain and osteosarcoma tumorigenesis." (PMID 39648148, 2024). "LC09-PPC/Cas9-VEGFA complexes facilitated selective delivery of CRISPR-Cas9 plasmid in both orthotopic osteosarcoma, resulting in VEGFA disruption." (PMID 37679807, 2023). "Recently, the impact of VEGFA status (gene copy number and protein overexpression) has been under investigation for some cancer types, such as osteosarcoma, colorectal, breast, and liver cancer." (PMID 37893095, 2023). "A recent study indicated that melatonin was able to regulate tumor angiogenesis through the miR-424/VEGFA signaling axis in osteosarcoma." (PMID 36825082, 2023). "in vitroin vivoAdditionally, miR-199a-5p can be transported from osteosarcoma cells to HUVECs through exosomes, thereby targeting VEGFA and inhibiting cell proliferation, migration and angiogenesis in vitro and in vivo." (PMID 35651811, 2022). "Both univariate and LASSO Cox regression analyses were conducted on screened module genes to identify 5 GCSRGs (RPS28, MCAM, EN1, TRAM2, and VEGFA) constituting a prognostic signature for osteosarcoma patients." (PMID 36618348, 2022). "The high level of VEGFA expression was related with poor overall survival and metastasis free survival in osteosarcoma patients." (PMID 35651811, 2022). "As a result, it decreased VEGFA expression and ultimately led to a decrease in osteosarcoma malignancy and lung metastasis." (PMID 35164379, 2022).
osteosarcoma (continued). "This system led to the selective delivery of CRISPR/Cas9 to osteosarcoma tumor cells providing effective VEGFA genomic editing." (PMID 35164379, 2022). "A whole-genome aCGH study of osteosarcoma samples demonstrated the association of copy number aberrations in 13 genes from VEGF pathway, including VEGFA amplification." (PMID 34209679, 2021). "Our results showed that compared with osteoblasts, AMBRA1 was down-regulated in U2OS and 143B, and while MYC and VEGFA were up-regulated in osteosarcoma cells." (PMID 34513835, 2021). "miR-134 targets the 3′-UTR of VEGFA and VEGFR1 and suppresses VEGFA/VEGFR1/AKT signaling to inhibit angiogenesis in osteosarcoma cells." (PMID 32993787, 2020). "A recent bioinformatic analysis of osteosarcoma miRNA signatures suggests that Bcl-2, VEGFA, CCDN1, PTEN, and Met are central driving factors in osteosarcoma." (PMID 33396725, 2020). "Currently, VEGFA has been reported to be very important in evaluating the angiogenesis in osteosarcoma." (PMID 32665038, 2020). "The LC09-fuctionalized nanocomposites achieved selective distribution of CRISPR/Cas9 in both orthotopic osteosarcoma and lung metastasis, and reduced VEGFA expression and secretion, thus inhibiting osteosarcoma malignancy and lung metastasis." (PMID 31892974, 2020). "The aim of this study was to evaluate the prognostic value of germline polymorphisms in key genes of the VEGF signaling pathway (VEGFA, FLT1 and KDR) in a prospective multicenter cohort of patients with localized high-grade osteosarcoma treated with the GEIS-33 protocol." (PMID 41471344, 2025). "High VEGFA expression indicates unfavorable prognosis in osteosarcoma patients." (PMID 38086608, 2024). "In the current study, G‐Rg5 showed strong binding energy with VEGFA (−8.4 kcal/mol), which suggested that G‐Rg5 could potentially inhibit the activity of VEGFA and VEGFA‐related pathways, and therefore suppress osteosarcoma growth and metastasis." (PMID 38086608, 2024). "This study shows that luteolin may regulate multiple signaling pathways by targeting various genes like AKT1, STAT3, IL6, TNF, and VEGFA to inhibit osteosarcoma proliferation and metastasis." (PMID 37749554, 2023). "VEGFA promotes the mTOR signaling in Osteosarcoma by promoting angiogenesis in the tumor." (PMID 37081847, 2023). "Studies performed on the detection of VEGFA status in osteosarcoma revealed that both FISH and IHC provide additional benefits in the eventual selection of patients candidates for anti-angiogenic treatment, whereas evaluation of only one of the two parameters proved to be insufficient or misleading." (PMID 37893095, 2023). "Also, FAP implies pro-angiogenic properties in osteosarcoma by promoting vascular endothelial growth factor-A (VEGF-A) expression." (PMID 37316886, 2023). "In addition, miR-199a-5p can be transported from osteosarcoma cells to HUVECs through exosomes, thereby targeting VEGFA and inhibiting the growth and angiogenesis of osteosarcoma." (PMID 35651811, 2022). "In addition, the expression of miR-199a-5p and VEGFA in osteosarcoma cells was negatively correlated." (PMID 35651811, 2022). "In addition, lncRNA MALAT1 sponged miR-150-5p and increased the expression of VEGFA and enhanced tumor angiogenesis in osteosarcoma." (PMID 35992869, 2022). "The high proportion of NCOR1 and VEGFA amplification may be a special molecular feature of Chinese osteosarcoma patients." (PMID 35756627, 2022). "Our results demonstrated that miR-199a-5p could be transported from osteosarcoma cells to HUVECs through exosomes, subsequently targeting VEGFA and inhibiting the growth and angiogenesis of osteosarcoma." (PMID 35651811, 2022). "first reported the vascular endothelial growth factor A (VEGFA) gene amplification in osteosarcoma patients from Tianjin, China, and pointed that increasing VEGFA expression is the biomarker for poor prognosis of Chinese osteosarcoma." (PMID 35756627, 2022).
osteosarcoma (continued). "In our previous study, complement-activated supernatant from NS-treated osteosarcoma cell lines demonstrated enhancement of angiogenesis in HUVECs through increased growth factor production, such as vascular endothelial growth factor-A and fibroblast growth factor-1." (PMID 33805189, 2021). "In basis of our results of in vitro experiments, we demonstrated that circPVT1 was obviously up-regulated in osteosarcoma tissues and cell lines, and circPVT1 could sponge miR-195 to up-regulate VEGFA expression to promote PTC progression." (PMID 34927541, 2021). "Inhibition of VEGFA can successfully suppress osteosarcoma growth, metastasis and angiogenesis." (PMID 32665038, 2020). "Finally, LC09 were chose as osteosarcoma cell-targeted aptamers, and LC09-modified lipopolymers loading CRISPR/Cas9 plasmids encoding VEGFA gRNA and Cas9 were developed." (PMID 31892974, 2020). "Indeed, VEGFA pathway has been prioritized for the development of antiangiogenic therapies in osteosarcoma." (PMID 32665038, 2020). "A single clinical trial is ongoing targeting VEGFA with bevacizumab in osteosarcoma (NCT00667342), however it is unclear whether this therapy is effective." (PMID 25347326, 2014). "In addition, considering G‐Rg5 had strong binding capacity with VEGFA by molecular docking, the anti‐angiogenesis and anti‐metastasis effects of G‐Rg5 on osteosarcoma could be another research direction." (PMID 38086608, 2024). "Experimental results showed that luteolin could inhibit cell viability and significantly decrease the expression of AKT1, STAT3, IL6, TNF, and VEGFA, and luteolin could also inhibit osteosarcoma proliferation and metastasis in osteosarcoma orthotopic mouse model." (PMID 37749554, 2023). "Hence, targeted VEGFA therapy is a key area for improving the osteosarcoma prognosis." (PMID 36618348, 2022). "Network pharmacology showed that 251 luteolin against osteosarcoma targets and 8 hub targets including AKT1, ALB, CASP3, IL6, JUN, STAT3, TNF, and VEGFA." (PMID 40066267, 2025). "VEGFA/VEGFR are the main targets for anti-angiogenic therapy; therefore, Mabs targeting VEGF are also widely used to treat solid tumors, especially osteosarcoma." (PMID 39252946, 2024). "Our RT-PCR results showed that IL-10, TGF-β1, VEGFA, and IGF-1 were significantly increased in osteosarcoma tissues." (PMID 32908942, 2020). "It is known that vascular endothelial growth factor-A (VEGF-A) plays a crucial role in angiogenesis and in osteosarcoma." (PMID 31719210, 2019). "The vascular endothelial growth factor-A (VEGF-A) pathway is the key regulator of angiogenesis and in osteosarcoma." (PMID 28406476, 2017). "Lastly, osteocytes as mature bone cells were also reported to have contributions to TME of osteosarcoma: osteocytes may have communications with osteosarcoma via the CXCL12-CXCR4 axis and by secreting TGF-β and VEGFA." (PMID 39582869, 2024). "Six of these genes are increased (MYOM2, VEGFA, MUC1, IHH, GLI1 and GRIA1) and seven are decreased (VCAM1, EGFR, GPC3, IGF2, GNG12, GNGT1 and C3) in localized patients with poor prognosis that either relapse or die due to osteosarcoma." (PMID 38538763, 2024). "Vascular endothelial growth factor A (VEGFA) is a potent angiogenic factor for blood vessel formation, and research has proved that VEGFA participates in the angiogenesis and progression of osteosarcoma." (PMID 37964984, 2023). "Several genomic characterization studies have pointed out that, although with a low incidence, amplification of the VEGFA gene locus is detectable in several cancer types, such as HCC, osteosarcoma, retinoblastoma, Merkel cell carcinoma, and carcinosarcoma and absent in healthy counterparts." (PMID 37893095, 2023). "In human osteosarcoma cells, CCL3 promotes angiogenesis by dysregulation of VEGFa." (PMID 35154316, 2022). "Vascular endothelial growth factor-A (VEGF-A), an angiogenesis inducer and a highly specific mitogen for endothelial cells, has not been well explored in human osteosarcoma." (PMID 26713602, 2016).
osteosarcoma (continued). "SPP1, VEGFA, EMMPRIN, MIF, uPAR, Angiogenin, and Cystatin C were among the most highly expressed analytes in both patient specimens and in cell line conditioned media, demonstrating that the osteosarcoma cells themselves are a cellular source of these molecules." (PMID 39896512, 2025). "Additionally, the interaction of VEGFA produced by osteoblastic osteosarcoma cells and CAFs can stimulate endothelial cell proliferation through VEGF receptor (VEGFR) binding, leading to a new vascular formation that supports osteosarcoma cell survival." (PMID 39359731, 2024). "Additionally, co-administration of TGT with EGFR inhibitors, STAT3 inhibitors, and VEGFA inhibitors may enhance the anti-osteosarcoma effects of TGT, further inhibiting the development and metastasis of osteosarcoma." (PMID 38297292, 2024). "However, until now, the osteosarcoma cell-secreted exosomal miR-199a-5p interaction with VEGFA in osteosarcoma has not been explored, especially in relation to angiogenesis." (PMID 35651811, 2022). "In another study, LC09 aptamer was used to specifically target the vascular endothelial growth factor A (VEGFA) of osteosarcoma cancer cells, by functionalizing LC09 aptamer with a PEG-PEI-Cholesterol (PPC) lipopolymer that encapsulated Cas9 and CRISPR/Cas9 plasmids coding for VEGFA gRNA." (PMID 32659966, 2020). "Vascular endothelial growth factor-A (VEGF-A) and vascular endothelial growth factor receptor-1 (VEGFR-1) are highly expressed by aggressive osteosarcoma cells, but not in clonally-related less aggressive cell lines." (PMID 27127605, 2016). "Indeed, we observed that HIF-1 target genes ANGPTL4, VEGFA, GLUT1, PGK1 and HK2 were down-regulated at mRNA level when DEC2 is knocked down in several osteosarcoma cell lines, while the mRNA level of HIF-1α showed no obvious change by the DEC2 knockdown." (PMID 25884381, 2015).